MEF2C (myocyte enhancer factor 2C)
Diseases named in the same sentence as MEF2C in open-access papers (continued):
Sharing a sentence is not in itself a finding about the gene and the disease.
breast carcinoma (28 papers, 2011 to 2025). "The 5q loss also includes FBXL17, a gene reported to be a biomarker for breast cancer resistance, and MEF2C, which was previously identified in association with breast cancer invasion." (PMID 25391423, 2015). "IL-4-activated macrophages co-cultivated with breast cancer cells without direct secreted miR-223-enriched microvesicles promoting the invasion of breast cancer cells via upregulating Mef2c." (PMID 36831498, 2023). "Perturbation of the miR-524-5p/MEF2C regulatory axis contributes to bone metastasis in prostate cancer and breast cancer." (PMID 36128051, 2022). "Among those DEGs, MEF2C showed the extremely high expression in patients with bone metastatic prostate and breast cancer." (PMID 36128051, 2022). "In contrast to miR-524-5p, MEF2C was upregulated in prostate and breast cancer with bone metastasis, and the MEF2C gene was predicted to be a target for miR-631, miR-524-5p, miR-330-3p, and miR-346." (PMID 36128051, 2022). "MEF2C was predicted to be regulated by miR-802-5p and miR-194-5p in brain metastases of breast cancer, which indicates that MEF2C plays a role in tumor metastasis." (PMID 36128051, 2022). "It has been reported that miR-223 enhances breast cancer invasion by inhibiting the expression of myocyte enhancer factor 2C (Mef2c) and increases the progression of gastric cancer by specifically targeting RhoB." (PMID 35757325, 2022). "MEF2C, a transcription factor, has been proposed as a new player in breast cancer brain metastasis development." (PMID 36128051, 2022). "Collectively, downregulation of miR-524-5p appears to be a precocious event in prostate and breast cancer, and MEF2C serves as a new player in prostate and cancer bone metastasis development." (PMID 36128051, 2022). "In conclusion, our data strongly suggest that downregulation of miR-524-5p appears to be a precocious event in prostate and breast cancer, and the miR-524-5p/MEF2C axis plays a novel role in bone metastases from prostate and breast cancers." (PMID 36128051, 2022). "M2-EVs promote cell invasion in breast cancer by transporting miR-223 to target the Mef2c/β-catenin pathway." (PMID 34975877, 2021). "Myocyte enhancer factor 2C (MEF2C) is increasingly expressed in mice along with breast cancer brain metastases (BCBM) development." (PMID 33673112, 2021). "IL-4 (Interleukin 4)-activated TAMs release exosomal miR-223, which favored invasion and aggressiveness in breast cancer cells by the activation of the Mef2c-βcatenin pathway (Myocyte enhancer factor 2c-βcatenin)." (PMID 31952362, 2020). "The reduction of Mef2c is related to nuclear accumulation of β-catenin to promote the invasiveness of the breast cancer cell lines." (PMID 30634952, 2019). "EVs containing high levels of miR-233 secreted by the TAMs can be transferred to breast cancer cells and promote their invasiveness by regulating the myocyte enhancer factor 2c (Mef2c)-β-catenin signaling pathway." (PMID 30634952, 2019). "Reducing Mef2c elicits nuclear accumulation of β-catenin to promote the invasiveness of breast cancer cells." (PMID 31766495, 2019). "A further recent study showed that macrophages can release exosomes carrying miR-223, which down-modulates the MEF2C (myocyte-specific enhancer factor 2C)-β-catenin pathway and enhances the invasiveness of breast cancer cells." (PMID 29652798, 2018). "In opposition to its antitumor role in HCC model, M2-derived miR-223 has been previously shown to stimulate proliferation in breast cancer cells because of the targeting of Mef2c/β-catenin pathway related to the inhibition of cell migration." (PMID 27349385, 2016). "For example, the MYC, miR-98 and LINC00665 motif was dysregulated only in breast cancer, while the MEF2C, miR-145 and JPX motif was dysregulated only in bladder cancer." (PMID 27322142, 2016). "The reduction of MEF2C is linked to nuclear accumulation of the function of β-catenin to promote the invasiveness of the SKBR3 and MDA-MB-231 breast cancer cell lines." (PMID 25563488, 2015).
breast carcinoma (continued). "In fact, p38, ERK5, and MEF2C itself have been recently described as novel downstream Brk (PTK6) effector pathways supposedly playing a role in primary breast cancer." (PMID 22952604, 2012). "Recently, MEF2C is established as a contributor to breast cancer brain metastasis." (PMID 40176070, 2025). "In this study, we found that MEF2C is upregulated in prostate and breast cancer bone metastasis." (PMID 36128051, 2022). "The regulatory effect of MEF2C on a variety of malignancies has been widely studied, including its role in the regulation of iron death in meningioma and its involvement in brain metastases of human breast cancer." (PMID 36338972, 2022). "In addition, the tumor-promoting role of miR-223 via modulating myocyte-specific enhancer factor 2C (MEF2C) has been established in breast cancer cells." (PMID 32992449, 2020). "A notable example of this aspect of TAM biology is the secretion of EVs containing high levels of miR-233, which can be transferred to breast cancer cells to promote their invasiveness by regulating the myocyte enhancer factor 2c (Mef2c)-β-catenin signaling pathway." (PMID 31766495, 2019). "Similarly, exosomes released by IL-4-activated macrophages, which specifically contain miR-233, can be transferred to breast cancer cells and promote their invasiveness by regulating the myocyte enhancer factor 2c (Mef2c)-β-catenin signaling pathway." (PMID 29302403, 2017). "The TF MEF2C is expressed in normal mammary epithelial cells and in breast cancer cell lines." (PMID 27322142, 2016). "The TF MEF2C interacts with the lncRNA JPX, miR-193a/b, miR-145, and miR-197, and every transcript in these structures is associated with breast cancer, suggesting they may play critical roles in tumorigenesis in combination with an L-FFL motif." (PMID 27322142, 2016). "Interestingly, exosome–transferred miR-223 stimulates the invasive behavior of breast cancer cells by targeting of Mef2c/β-catenin pathway, thus leading to increase cell migration." (PMID 27349385, 2016). "It has been reported that miR-223 could promote breast cancer invasiveness by suppressing Mef2c (Myocyte enhancer factor 2c)." (PMID 25881295, 2015). "miR-223 transferred to breast cancer cells targets the 3′-UTR of MEF2C, a myocyte enhancer factor." (PMID 25563488, 2015). "MEF2C is a transcriptional enhancer whose biological function in human breast cancer is still unknown." (PMID 22952604, 2012). "To understand the mechanism by which miR-223 promotes breast cancer cell invasion, we assessed whether miR-223 targets Mef2c in breast cancer cells." (PMID 21939504, 2011). "It is interesting to note that, MEF2C, one of the members of the MEF2 family, was recently reported to be involved in the development of breast cancer brain metastases (BCBM)." (PMID 38791246, 2024). "Previous studies from our laboratory using a mouse model of brain metastases development from triple negative breast cancer (TNBC) revealed that microRNAs 802-5p and 194-5p are downregulated in plasma prior to detection of BM from BC and that MEF2C is a target of both miRNAs." (PMID 33673112, 2021). "MEF2C emerged as their relevant target, with an increasing expression along BCBM expansion and in resected brain metastasis from breast cancer patients." (PMID 31930767, 2020). "Barcode validation results for differential over-expression of MEF2C, SMAD3 and POU2AF1 within two platforms for several gene-probes in different breast cancer tissues." (PMID 22952604, 2012). "In neuroblastoma and mesothelioma, ERK5 is activated by PI3K/AKT signaling; in breast cancer, STAT3 enhances MEK5 expression; and in renal epithelial cells, TGFβ1-induced MEK5/ERK5 activation occurs through ALK and p38 MAPK, facilitating MEF2C-mediated transcription." (PMID 40672381, 2025). "Gene expression validation for MEF2C and MNDA in breast cancer samples." (PMID 22952604, 2012).
breast carcinoma (continued). "In this paper, we have analyzed the role that thermodynamic fluctuations in energy at the cell-level play in the synthesis of transcription factors MNDA, POU2AF1, MEF2C and SMAD3 and how can this energetic constrains be related with the presence of primary breast carcinomas." (PMID 22952604, 2012). "In the luminal B (LumB) subtype of breast cancer, lncRNA LIPR-AS1 cooperative genes IL1R and TGFBR, which are upstream of the MAPK signaling pathway, share a common grade junction pathway (p38 MAPKs-MEF2C), which induces the proliferation, differentiation and apoptosis of cells." (PMID 36233210, 2022).
autism (26 papers, 2010 to 2025). Persistent deficits in social interaction and communication and interaction as well as a markedly restricted repertoire of activity and interest as well as repetitive patterns of behavior. "An overlay between the nearest gene for active autism-associated enhancers and active enhancers in each of the three MEF2C microglial genotypes identified the greatest overlap with MEF2C-KO microglia." (PMID 41125877, 2025). "For example, MEF2C, a transcription factor activated during the transition from prenatal to postnatal neurons, aligns expression patterns with autism risk genes." (PMID 39363111, 2024). "MEF2C is among the genes from SFARI Gene noted as a syndromic cause of autism and is differentially expressed here by DHT." (PMID 30104728, 2020). "Coufal and colleagues generated microglia from human iPS cells to examine mechanistic roles of the transcription factor MEF2C and how these roles might relate to the autism phenotype seen following the loss of MEF2C in human microglia." (PMID 41125877, 2025). "We identified 47 autism-risk genes that were predicted to be targeted by MEF2C." (PMID 39363111, 2024). "Moreover, decreased function of Mef2c is associated with a possible microglial activation that is sufficient to induce autism-like symptoms in mice." (PMID 35203447, 2022). "Overall, our RNAseq data analysis suggests that MEF2C, either directly or indirectly, influences a large, complex gene expression program that influences neuronal and synapse development, and numerous syndromic and idiopathic autism-linked genes." (PMID 27779093, 2016). "It will be interesting to determine whether translational regulation of human MEF2C is also important in the nervous system, where MEF2C is associated with autism and synaptic regulation." (PMID 24143132, 2013). "Within prenatal development MEF2C has the potential to be a transcriptional regulator of a number of autism-associated genes— MEF2C binding motifs are enriched in upstream regions of genes within prenatal gene co-expression modules that harbor a number of autism-associated genes." (PMID 30104728, 2020). "A recent study found that global Mef2c+/– heterozygous mutant mice display autism-related behaviors and deficits in cortical excitatory synaptic transmission." (PMID 41125877, 2025). "In other brain regions, key autism susceptibility genes included FOXP1 (caudate and putamen), MEF2C and SATB2 (cortical plate), and TBR1 and NR4A2 (subplate)." (PMID 41279531, 2025). "The knock-down of NDIME led to the downregulation of the MEF2C gene, which is considered to be involved in the pathogenesis of autism." (PMID 40868063, 2025). "Transcriptomic and epigenetic approaches identified substantial overlap with idiopathic autism datasets, suggesting a broader role of human microglial MEF2C dysregulation in idiopathic autism." (PMID 41125877, 2025). "Matrisciano and coworkers demonstrated changes in the expression of genes involved in excitatory and inhibitory neurotransmission including MEF2C in a mouse model of idiopathic autism." (PMID 36834528, 2023). "It is noteworthy in this context that heterozygous Mef2c mice display autism-related behaviors, similar to L1-heterozygous mice." (PMID 35408913, 2022). "Compatible with effects on early neurogenesis and differentiation, we find evidence that MEF2C expression is dysregulated in the same direction as FT influence in iPS cells in male cases with autism." (PMID 30104728, 2020). "Congruent with the directionality of DHT upregulation, MEF2C is also upregulated in iPSCs from male patients with autism (t = 3.68, p = 0.0035, Cohen’s d = 1.42)." (PMID 30104728, 2020). "MEF-2c mutants showed significant overlap of synaptic and autism-linked genes in the cortex and mutant mouse models displayed autism and schizophrenia-like behavior, suggesting functional importance of MEF-2C in the neo-cortex." (PMID 31105874, 2019).
autism (continued). "Similarly, the lncRNA LINC00461 and its mouse homologue NDIME, which were found to be associated with autism and ADHD, regulate the expression of the MEF2C gene, which encodes a transcription factor, the myocyte-specific enhancer factor 2C." (PMID 40868063, 2025). "We found enrichment of genetic variants in autism and neuropsychiatric disorders in regulatory enhancers upregulated with loss of MEF2C, specifically associated with MEF2C activation and not repression." (PMID 41125877, 2025). "In the present study, one autism-related CNV deletion gene was identified : MEF2C." (PMID 28533427, 2017). "Mef2c cKO mice also show significant increases in repetitive motor behaviors and overall hyperactivity – all symptom domains with potential relevance to human neurodevelopmental disorders such as autism, ID and SCZ." (PMID 27779093, 2016). "Loss of MEF2C alters the gene expression, directly or indirectly, of numerous autism- and synapse-linked genes and RNAs known to associate with FMRP, the leading genetic cause of ID and autism." (PMID 27779093, 2016). "Thus, the results of the present study provided evidence that the MEF2C deletion might be a factor for the induction of autism." (PMID 28533427, 2017). "Finally, the Mef2c cKO mice display multiple behavioral phenotypes that are reminiscent of core autism symptoms in humans, including abnormal social behaviors, reduced USVs in multiple ages and contexts, and an increased frequency of some repetitive motor behaviors." (PMID 27779093, 2016). "In an important link with autism, we find similar MEF2C upregulation in iPS cells, but not neural progenitor cells or neurons from male cases of autism." (PMID 30104728, 2020). "Finally, we tested whether MEF2C is dysregulated in induced pluripotent stem cells (iPSC) from male patients with autism and whether the directionality of such dysregulation is congruent with the directionality of DHT-influence on MEF2C expression." (PMID 30104728, 2020).
Alzheimer disease (25 papers, 2015 to 2026). A progressive, neurodegenerative disease characterized by loss of function and death of nerve cells in several areas of the brain leading to loss of cognitive function such as memory and language. "MEF2C has been implicated in multiple neuropsychiatric phenotypes and disorders, including autism spectrum disorder, schizophrenia, and Alzheimer’s disease." (PMID 33905376, 2022). "In support of these findings, variants in the proximity of both SPI1 and MEF2C have earlier been identified as significant Alzheimer’s disease risk loci." (PMID 33568722, 2021). "Genome-wide association studies (GWAS) have shown the linkage between mutation of MEF2C and aging-associated late-onset Alzheimer's disease." (PMID 33869630, 2021). "Myocyte Enhancer Factor 2C (MEF2C) is identified as a candidate gene contributing to the risk of developing Alzheimer’s disease." (PMID 34386032, 2021). "Studies in older adults have linked variation in MEF2C gene to the risk of multiple neurological disorders, such as Late Onset Alzheimer’s disease (LOAD) and Parkinson’s disease." (PMID 34386032, 2021). "Mef2c is also a candidate risk gene for various neurodevelopmental disorders such as schizophrenia, major depressive disorder and Alzheimer’s disease." (PMID 32714604, 2020). "A common single nucleotide polymorphism (SNP, rs190982) in MEF2C gene was identified to be related to late-onset Alzheimer's disease (LOAD) in Caucasians in a large meta-analysis of genome-wide association studies (GWAS)." (PMID 27276684, 2016). "We highlight that sysMPRA effectively uncovers regulatory effects stemming from the disruption of MEF2C transcription factor binding sites, single-nucleotide polymorphisms, and the consequences of genetic variations associated with late-onset Alzheimer‘s disease." (PMID 40270544, 2025). "Mef2c has been identified in human genetic analysis as a susceptibility gene associated with many neurological diseases and is one of the biomarker genes for Alzheimer’s disease." (PMID 32499679, 2020). "MEF2C downregulation has been reported in multiple neurological disorders, including ischemia-reperfusion injury, Alzheimer’s disease, and spinal cord injury." (PMID 41390720, 2025). "The association between MEF2C and cognitive disorders is extremely similar to the role of MEF2C in autism spectrum disorders and Alzheimer’s disease." (PMID 38827438, 2024). "A previous study reported neuronal Mef2c limited excessive synapse formation during synaptic refinement, while Mef2c was revealed to promote neuronal resilience against Alzheimer's disease (AD) pathology via preserving synapse integrity and plasticity." (PMID 39648651, 2024). "MEF2C has reported roles in numerous age-related conditions, including Alzheimer’s disease and muscle wasting in cancer and GRM is associated with age-related hearing loss." (PMID 36975205, 2023). "Representative examples are triggering receptor expressed on myeloid cells-2 (Trem2), Cd33, Cr1, Mef2c, members of the MS4A family, and the HLA locus, which are Alzheimer’s disease (AD) risk genes." (PMID 31627485, 2019). "In hypothesis-driven tests, there was significant association between general cognitive function and four genes previously associated with Alzheimer's disease: TOMM40, APOE, ABCG1 and MEF2C." (PMID 25644384, 2015). "MEF2C is involved in the development of various neuropsychiatric disorders, such as autism spectrum disorder (ASD), schizophrenia (SCZ), and Alzheimer’s disease (AD)." (PMID 39920775, 2025). "Transcriptional changes in neurons in Alzheimer's disease (AD) are specifically regulated by MEF2C, without the involvement of other members of the MEF2 family." (PMID 38478029, 2024).